NDRG1 (N-myc downstream regulated 1)
Diseases named in the same sentence as NDRG1 in open-access papers (continued):
Sharing a sentence is not in itself a finding about the gene and the disease.
tumor (continued). "Collectively, the findings in our study demonstrated that the promising novel anti-tumor agent, DpdtC that can up-regulate NDRG1 and target HER2-ERK1/2 pathway, has the potential to provide a new therapeutic strategy in HER2-overexpressing cancer treatment." (PMID 29467385, 2018). "NDRG1, a tumor suppressor, was also shown to inhibit cancer metabolism in PDAC partly through the regulation of GLUT1 gene." (PMID 29515771, 2018). "Previously, NDRG1 has been inferred as a tumor suppressor gene in NPC due to knockdown of NDRG1 promoted NPC cell proliferation, migration, and invasion of EBV-negative (Epstein-Barr virus) NPC 5-8F cells in vitro." (PMID 29738439, 2018). "NDRG1 belongs to the NDRG (N-myc downstream-regulated gene) family which has been reported to function as a tumor and metastasis suppressor gene in several types of cancer including breast, pancreatic and prostate cancers." (PMID 29467385, 2018). "Previous studies have demonstrated that thiosemicarbazones were able to exert anti-tumor effects through up-regulating NDRG1 expression." (PMID 29467385, 2018). "In our research, we found that NDRG1 plays an important role in mediating the anti-tumor effects of DpdtC in HER2-overexpressed cancer cells through inhibiting the formation of HER2/EGFR heterodimer." (PMID 29467385, 2018). "The molecular mechanisms of anti-tumor activity of NDRG1 involve its suppressive effects on a variety of tumorigenic signaling pathways." (PMID 28537875, 2017). "N-myc downstream-regulated gene 1 (Ndrg1) was related to tumor progression and metastasis and its induction by EGb in the present study is potentially the key factor that interacts with both WNT pathway and Myc network." (PMID 29197355, 2017). "NDRG1, a tumor suppressor and metastasis blocker, and ADM, which has been reported to have anti-migratory effects, were also significantly upregulated with BIX-01294." (PMID 29145444, 2017). "Initially, our data showed that NDRG1 was inversely correlated to tumor sizes, local invasion and TNM stage." (PMID 29137287, 2017). "Our data showed a significant inverse correlation between NDRG1 and tumor size (R = -0.355, P = 0.001), local invasion (R = -0.318, P = 0.002), lymphatic invasion (R = -0.287, P = 0.005) and TNM stage (R = -0.287, P = 0.005)." (PMID 28537875, 2017). "Numerous genes known to be highly expressed in proliferating cells (Tfrc, metallothioneins genes) were upregulated by the HPD while tumor suppressor genes (Ppp2r2a, Ndrg1 and Prdx1) were downregulated by the HPD (q < 0.01)." (PMID 28137254, 2017). "A number of research groups have shown that NDRG1 over-expression decreases tumor growth, reduces invasion and suppresses metastasis." (PMID 28045438, 2017). "The metastasis suppressor NDRG1 is negatively correlated with tumor progression of several types of cancer, and most importantly down-regulation of NDRG1 expression enhances cell proliferation and invasiveness." (PMID 27894074, 2017). "To gain insight into the mechanisms of significant tumor regression in NDRG1-positive patients, we detected altered activities in several apoptotic pathways via a pathscan array using protein extracted from selected specimens." (PMID 28537875, 2017). "NDRG1 expression has been shown to be increased by a variety of environmental stresses, including hypoxia, in either normal or tumor cells, and is involved in caspase activation and apoptosis." (PMID 28046107, 2017). "As shown, NDRG1 mRNA levels were significantly decreased in tumor tissues relative to matched normal tissues." (PMID 29137287, 2017). "NDRG-1 protein expression can be silenced by abnormal DNA methylation of the gene promoter and modify tumor aggressiveness." (PMID 26894863, 2016). "The N-myc downstream regulated gene (NDRG) family of NDRG1, 2, 3, and mammary serine protease inhibitor (Maspin) gene are well-known modulators in the neoplasia process." (PMID 27589737, 2016).
tumor (continued). "We observed that only the combination of BYL719 and SGK1-inh reduced tumor burden and phosphorylation of S6, 4EBP1, and NDRG1." (PMID 27451907, 2016). "Positive methylation of NDRG-1 in tumor tissue was marginally associated with a decreased risk of DFS (HR=0.55; 95% CI: 0.28, 1.05; p = 0.071), while PHLDA-3 methylation in tumor tissue increased the DFS risk (HR=2.21; 95% CI: 0.97, 5.02; p = 0.058)." (PMID 26894863, 2016). "Tumor angiogenesis and the number of infiltrating macrophages in the tumors were also found to be significantly (**P < 0.01, *P < 0.05) reduced in Ndrg1 KO mice compared to WT mice." (PMID 26778110, 2016). "In this study, we demonstrated the involvement of NDRG1 in tumor progression, especially tumor angiogenesis, through enhancing the differentiation of tumor-associated macrophages." (PMID 26778110, 2016). "Together, these results suggest that NDRG1 promotes tumor growth and angiogenesis, which is accompanied by the infiltration of macrophages into the tumor." (PMID 26778110, 2016). "Previously, our studies indicated that NDRG1 plays a critical role in tumor adaptation to oxygen fluctuations." (PMID 26852918, 2016). "NDRG1, a suppressor of metastasis is recently shown to inhibit c-Src and downstream signaling pathways in three tumor cell-types." (PMID 26993602, 2016). "Studies were performed with all 4 clones (i.e., NDRG1 Con, NDRG1, sh Con, sh NDRG1) and the growth of the resultant tumor xenografts was monitored every 5 days for 30 days using Vernier calipers (n = 5–15 mice/group)." (PMID 26418878, 2015). "NDRG1, as a tumor suppressor, is negatively correlated with tumor progression and inhibits tumor cells metastasis in multiple neoplasms." (PMID 25213357, 2015). "In fact, a novel class of pharmacological agents were found to significantly up-regulate NDRG1 expression in a range of neoplasms." (PMID 26431493, 2015). "NDRG1 is a multifunctional protein involved in tumorigenesis and tumor development, and its function differs in different tumor-types." (PMID 26431493, 2015). "NDRG1 is a tumor suppressor that inhibits tumor progression and metastasis, and overexpression of NDRG1 has been shown to exert an anti-metastatic effect." (PMID 26453548, 2015). "Significant up-regulation of NDRG1 was observed in HCC tissues compared to adjacent non-tumor liver tissues at both mRNA and protein levels, and it has also been suggested as a novel biomarker of liver cancer recurrence." (PMID 26359353, 2015). "NDRG1 expression was negatively related to tumor invasion (p = 0.022) and lymphatic metastasis (p = 0.011)." (PMID 26418878, 2015). "N-myc downstream-regulated gene 1 (NDRG1) is a potent metastasis suppressor in multiple tumor-types." (PMID 26418878, 2015). "It has been reported that NDRG1 is involved in tumor metastasis and, hence, negatively correlates with tumor progression in multiple neoplasms." (PMID 25213357, 2015). "Significant advances have been made in recent years in terms of dissecting the molecular mechanism by which NDRG1 exerts its tumor growth and metastasis suppressive activities." (PMID 26125440, 2015). "Currently, NDRG1 is being considered as an important oncogenic target of a new group of potent anti-tumor chemotherapeutics belonging to the DpT class, which include Dp44mT and DpC." (PMID 25860930, 2015). "Only 2 CRC tissues expressed a similar level of NDRG1 to that observed in the paired non-tumor tissues." (PMID 23874544, 2013). "The clinical significances of tumor metastatic suppressor, N-myc downregulated gene 1 (NDRG1), have been inconsistently reported in a variety of cancerous diseases." (PMID 23874544, 2013). "We and others demonstrated that NDRG1 is a novel tumor metastatic suppressor in different tumor cells including CRC." (PMID 23874544, 2013). "In gastric cancer, NDRG1 promotes tumor metastasis through epithelial-mesenchymal transition (EMT) by upregulating the expression of vimentin and Snail and downregulating the expression of E-cadherin." (PMID 24260043, 2013).
tumor (continued). "In this study with 240 CRC clinical specimens, we showed that NDRG1 expression was significantly decreased in most of CRC tissues compared to the paired non-tumor counterparts." (PMID 23874544, 2013). "NDRG1 has also been shown to affect the TGFβ pathway, leading to the up-regulation of two key tumour suppressor proteins, namely PTEN (phosphatase and tensin homologue deleted on chromosome 10) and SMAD4." (PMID 23634903, 2013). "Forced over-expression of NDRG1 into neuroepithelioma cell line results in reduced cell size and soft agar growth, implying the tumor suppressor role of NDRG1 in NB." (PMID 24269992, 2013). "NDRG1 exerts its function through modulating the major signaling pathways in a large variety of tumor types including CRC." (PMID 23874544, 2013). "NDRG1 is involved in cellular differentiation, proliferation, and growth arrest, as well as neoplasia, tumor progression and metastasis, heavy metal responses, the hypoxia response, and DNA damage response." (PMID 23762858, 2013). "Statistical analysis revealed a significant inverse correlation of NDRG1 expression with tumor stage, differentiation status and metastasis." (PMID 23874544, 2013). "Our results indicate that FOXD3 exhibits tumor suppressive activity that affects the growth, aggressiveness and angiogenesis of NB through transcriptional regulation of NDRG1." (PMID 24269992, 2013). "Recent evidence has shown that NDRG1 is inducible by a variety of factors and stimuli related to cancer progression, including oncogenes, tumor suppressors, and hypoxic microenvironment." (PMID 24269992, 2013). "The N-myc downstream regulated gene 1 (NDRG1), a putative tumor suppression gene, is involved in the regulation of human cell differentiation and metastasis in various cancers." (PMID 23899187, 2013). "Finding that an Akt inhibitor robustly suppresses NDRG1 phosphorylation would indicate that the tumour has high Akt, but low SGK1, activity." (PMID 23581296, 2013). "Comparing tumor growth rates of As1/Mock3, As1/Sic50 and As1/Sic54 cells in a xenograft model revealed slower tumor growth rates of both As1/Sic50 and As1/Sic54 by NDRG1 knockdown." (PMID 22844455, 2012). "Our results revealed the dynamic nature of gene expression in MCF-7 cells upon reoxygenation and demonstrated that NDRG1 is involved in tumor adaptation to reoxygenation." (PMID 21912630, 2011). "Lovastatin's involvement in the AKT-signaling pathway was confirmed by an upregulation of its downstream target, tumor progressor NDRG1." (PMID 20205716, 2010). "WalBC cells also over expressed the tumor metastasis suppressor NDRG1, which has been shown to be negatively correlated with tumor metastasis." (PMID 18179684, 2008). "In some cancers, NDRG1 has been proposed to be a tumour marker because it is highly expressed in malignant compared to normal tissue of the same origin." (PMID 16832411, 2006). "NDRG1 expression is also modulated by ascorbate levels within a tumour microenvironment, directly demonstrating an alternative mechanism of its regulation." (PMID 16832411, 2006). "Initially, our data in the pancreas were consistent with previous reports on other cancers, showing that NDRG1 protein is highly expressed in tumours compared to normal tissue of the same origin." (PMID 16832411, 2006). "Overexpression of NDRG1 in vitro results in morphological changes typical of cell differentiation and is inversely related to tumour growth and metastasis." (PMID 16832411, 2006). "In comparison, there was nominal staining for NDRG1 in tumours that lost histopathological signs of differentiation (G3, n=9)." (PMID 16832411, 2006). "Our profiles indicate that RARβ2 induces a number of tumor suppressor functions (NDRG1, RPL10, and ST18) and known metastasis suppressors (NDRG1 and TYRP1)." (PMID 16255778, 2005). "Because of its differential expression in cancer tissues and the high stability of the protein, Ndrg1 is proposed as a useful new tumour marker." (PMID 15341671, 2004).
tumor (continued). "In the majority of human tissues studied, Ndrg1 protein is overexpressed in cancers compared to normal tissues and also reflects tumour hypoxia better than HIF-1 protein." (PMID 15341671, 2004). "Ndrg1 preferentially stained the tumour cells adjacent to the necrotic areas which were supposed to be hypoxic." (PMID 15341671, 2004). "NDRG1 contributes to tumor aggressiveness by cell proliferation and lipid metabolism regulation, whereas GAPVD1, INPP5A, TCN1, SAV1, RBBP8, SPIB, and UBE2A also exhibit oncogenic or tumor-suppressive properties associated with prognosis." (PMID 41511940, 2026). "In the present work, we apply our image analysis pipeline to multiplexed immunofluorescence images of chemotherapy-treated PDAC xenografts, focusing on the spatial distribution of phosphorylated NDRG1 (pNDRG1) and the proliferation marker Ki67 in cancer cells within stroma-rich tumor regions." (PMID 40980692, 2025). "Additionally, we clustered epithelial cells into tumor and normal groups, revealing that NDRG1 is mainly expressed in malignant cells." (PMID 40539245, 2025). "In the current study, we hypothesized that drugs with transcriptomic signatures analogous to NDRG1 knockdown under TGFβ stimulation could exert anti-tumor effects in TNBC." (PMID 40612674, 2025). "Based on our previous findings, we investigated whether tumor cell‐derived NDRG1 and lactate influence histone H3K18 lactylation (H3K18la) in macrophages and its role in regulating immunosuppressive genes." (PMID 40539245, 2025). "In contrast, full-length NDRG1 accounts for the tumour-promoting role of this protein." (PMID 40332138, 2025). "Interestingly, N-myc downregulated gene 1 (NDRG1), a tumor and metastasis suppressor, was significantly (q < 0.0001) upregulated in MeG-treated MCF-7 cells." (PMID 40733287, 2025). "In this tumour type, NDRG1 regulates EMT through its interaction with caveolin-1." (PMID 40332138, 2025). "Our results show that both NDRG1 knockdown and αPD‐L1 monotherapy (200 μg per mouse, administered intraperitoneally every three days for a total of five doses) significantly inhibited tumor growth." (PMID 40539245, 2025). "In addition, the expression of NDRG1 (N-myc downstream regulated 1) mRNA, a potent tumor and metastasis suppressor, was significantly upregulated (8.5 fold and q < 0.0001) in MeG-treated MCF-7 cells." (PMID 40733287, 2025). "Furthermore, NDRG1 can mitigate Erastin-induced ferroptosis and promote tumor progression, with eight genes, including HSPA8 and CDH1, potentially being part of its underlying molecular mechanisms." (PMID 40386780, 2025). "Overall, these studies support the role of NDRG1 as a tumour suppressor." (PMID 40332138, 2025). "For instance, di-2-pyridylketone 4,4-dimethyl-3-thiosemicarbazone (Dp44mT) and di-2-pyridylketone-4-cyclohexyl-4-methyl-3-thiosemicarbazone (DpC) have been extensively shown to upregulate NDRG1 expression, leading to metastasis suppression and inhibition of tumor growth in multiple cancer models." (PMID 40378957, 2025). "Meanwhile, the expression level of NDRG1 increased along with the tumor stage." (PMID 38182978, 2024). "Additionally, using publicly available datasets, NDRG1 expression was shown to be higher in BrM compared with the corresponding primary tumours." (PMID 40530439, 2024). "Additionally, HER2+ and TNBC cases contained a much higher proportion of NDRG1 high cases, whereas ER+ tumours had an equal proportion of NDRG1 high and low expressions." (PMID 40530439, 2024). "NDRG1 has been described as a metastasis suppressor across different tumour types." (PMID 37854018, 2024). "Furthermore, cells overexpressing full-length NDRG1 exhibited a significantly accelerated tumor formation, while its N-terminally truncated isoforms showed significantly impaired capacity to form tumors." (PMID 38983911, 2024).
tumor (continued). "The positive correlation between NDRG1 and both MVD and VM may provide the first evidence that NDRG1 can induce tumor angiogenesis and VM in UC which may offer a novel pathway for further therapeutic strategies." (PMID 38561462, 2024). "Importantly, both N-terminally truncated NDRG1 isoforms prevented limited tumor growth, highlighting the critical role of the N-terminal region in its oncogenic function, potentially affecting NDRG1 interactions or stability." (PMID 38983911, 2024). "This means that NDRG1 upregulation can be considered as a marker of the activation of specific biological processes that may cooperate in TNBC by promoting tumor progression and relapse." (PMID 39736699, 2024). "In this study, we describe a different expression of NDRG1 in different BC tumor subtypes, as assessed by proteomics, RNA-Seq, and IHC, but also provide evidence of the upregulation of NDRG1 in BC tumor tissues compared to the normal counterpart in support for the possible oncogenic role of NDRG1." (PMID 39736699, 2024). "However, the restoration of NDRG1 counteracted the inhibitory effect of NSUN6 downregulation on tumor growth." (PMID 38970106, 2024). "Conversely, a complete absence of NDRG1 also demonstrated a significant association with poor survival, arguing for its role as a tumour suppressor." (PMID 40530439, 2024). "We then investigated NDRG1 expression in a cohort of BC to BrM tumours using immunohistochemistry." (PMID 40530439, 2024). "Increasing evidence indicates the oncogenic role of NDRG1 in different tumor types including TNBCs." (PMID 39736699, 2024). "Interestingly, it has been reported that NDRG1 can modulate tumor growth and angiogenesis through regulating the angiogenic “on- or off-switch” of the tumor stroma." (PMID 38561462, 2024). "Additionally, knocking down Ndrg1 in BLM tumor organoids reduced secretory progenitor marker gene expression (Sox4, Atoh1, Dll1, Notch1), but increased enterocyte marker gene expression (Cdhr2, Aqp8)." (PMID 38893159, 2024). "This inhibitory effect has been validated in various tumor cells, indicating that NDRG1 may participate in tumor immune evasion and inflammation by regulating the NF-κB pathway." (PMID 39668822, 2024). "RNAseq analysis of the same tumor cohort confirmed the overexpression of NDRG1 in TNBC compared to Luminal samples according both to the PAM50 classification (FDR = 1.25E−08, log2FC = 3.36) and the immunohistochemical classification (FDR = 1.997E−05, log2FC = 3.16)." (PMID 39736699, 2024). "In summary, we demonstrated that lncMEG3 could upregulate the expression of NDRG1 by relieving the suppression capabilities of miR-9-5p and thereby inhibit tumor proliferation and promote apoptosis in PCa." (PMID 38271137, 2024). "Importantly, full-length NDRG1 overexpression in MDA-MB-231 cells enhanced tumor growth, whereas NDRG1 knockout and overexpression of the N-terminally truncated NDRG1 isoforms significantly reduced tumor growth." (PMID 38983911, 2024). "Within the tumour grades, high NDRG1 expression was enriched for Grade 3 tumours." (PMID 40530439, 2024). "However, like NDRG1, patients with aggressive tumor types such as ER– and basal-like tumors expressed higher levels of NDRG2 relative to those with ER+ tumors and non-basal subtypes (p < 0.0001)." (PMID 38611020, 2024). "NDRG1 expression was first compared between the primary BC and secondary BrM tumours." (PMID 40530439, 2024). "The most studied functions of NDRG1 include tumor metastasis and hypoxia." (PMID 39092227, 2024). "To validate this hypothesis, we first investigated the role of NDRG1 on metastatic features of tumor cells." (PMID 36594086, 2023). "Furthermore, to corroborate these findings at the protein level, we conducted Western blotting and IHC analyses, both of which confirmed the heightened protein expression of NDRG1 in tumor tissues." (PMID 38235128, 2023).